NYX (nyctalopin)
Description:
Required for normal vision. Is a critical factor for light-induced depolarization of retinal ON-bipolar cells, likely acting as a scaffold for TRPM1 and GRM6. Required for TRPM1 trafficking to dendritic tips of ON-bipolar cells.
Synonyms: CLRP; CSNB1A; CSNB1; CSNB4; NBM1
Tractability: Antibody: UniProt places it where antibodies can reach, with medium confidence; UniProt predicts a signal peptide or a membrane-spanning region; its Gene Ontology location is reachable by antibodies, with medium confidence.
Gene: Protein-coding gene on chromosome X (41,445,383 to 41,475,710, forward strand). Ensembl gene ENSG00000188937.
Subcellular location: Secreted, extracellular space, extracellular matrix; Cell projection, dendrite; Postsynapse
Gene Ontology:
Molecular function: protein binding; signaling receptor activity
Biological process: visual perception
Cellular component: extracellular matrix; gel phase of interstitial matrix; postsynapse; dendrite
Homologues: Orthologues: chimpanzee NYX (99% identical), macaque NYX (96% identical), rabbit NYX (89% identical), dog NYX (87% identical), guinea pig NYX (86% identical), mouse Nyx (85% identical), rat Nyx (83% identical), pig NYX (64% identical), zebrafish nyx (51% identical), tropical clawed frog nyx (51% identical). Paralogues in human: PODN (25% identical), RTN4R (24% identical), RTN4RL2 (24% identical), PODNL1 (24% identical), LRRC15 (22% identical), FLRT1 (22% identical), LRRTM4 (22% identical), RTN4RL1 (22% identical), FLRT2 (21% identical), LRRC4B (21% identical), LRRC4 (21% identical), LRRTM3 (21% identical), and 10 more.
Diseases named in the same sentence as NYX in open-access papers:
NYX is named in the same sentence as 33 diseases in open-access papers, as found by Europe PMC text mining. Sharing a sentence is not in itself a finding about the gene and the disease. The quoted sentences say what the papers report.
myopia (13 papers, 2007 to 2026). "High myopia was associated with the NYX (n = 4, −8.34 ± 1.75D), RPGR (n = 3, −8.63 ± 2.69D) and TRPM1 (n = 3, −8.92 ± 2.63D) genes." (PMID 41465105, 2025). "Early-onset myopia was more common in patients with mutations of NYX, GRM6, and TRPM1 than in patients with CACNA1F mutations, further supporting the link between the mGluR6 signaling pathway and myopia." (PMID 38448886, 2024). "According to our three cases of the complete type, two cases of NYX gene mutations showed high myopia and poor visual acuity, whereas one case of TRPM1 gene mutations showed high myopia but retained visual acuity." (PMID 34064005, 2021). "Phenotype analysis of patients with mutations in the NYX gene further documented that myopia in these patients is associated with the complete form of CSNB1." (PMID 17392683, 2007). "Whether the development of high myopia in cCSNB depends on the type and location of NYX variants remains to be elucidated." (PMID 41729106, 2026). "It is suggested that disruptions in NYX cause aberrant retinal signalling, mimicking retinal blur that could cause abnormal elongation of the eye and subsequent high myopia." (PMID 41153400, 2025). "Patients with autosomal recessive cCSNB and NYX mutation often have high myopia, while those with autosomal recessive iCSNB and CACNA1F mutation may develop myopia or hyperopia." (PMID 37835784, 2023). "Besides night blindness, high myopia is also frequently documented as a typical sign in CSNB1A patients with NYX mutations." (PMID 19862333, 2009). "Our results align with previous studies, such as Hendriks and associates’ findings on CSNB patients, who demonstrated high myopia, especially in those with mutations in the CACNA1F, NYX, and TRPM1 genes." (PMID 40935931, 2025). "Igelman and associates focused on the progressive aspect of myopia among CSNB paediatric patients, analysing samples of 78 paediatric patients with CSNB, out of which 41 with CACNA1F, 22 with NYX and 15 with TRPM1 genes." (PMID 40935931, 2025). "Many patients with cCSNB are found to have myopia, especially in those patients carrying with GRM6 and NYX mutations." (PMID 38448886, 2024). "Nyctalopin is unique among SLRPs as it is GPI-anchored to the plasma membrane, and X-linked- Mutations in NYX cause X-linked congenital stationary blindness, affecting night vision, myopia, and visual acuity." (PMID 41281748, 2025). "Recently, mutations in NYX have been reported to associate with high myopia alone without night blindness." (PMID 19862333, 2009). "Two unrelated male individuals with high myopia but without night blindness were found to have novel Cys48Trp and Arg191Gln mutations in NYX." (PMID 17392683, 2007). "We report here novel mutations in the NYX genes in two unrelated male individuals with myopia alone without night blindness." (PMID 17392683, 2007). "Additionally, studies investigating patient cohorts with high myopia (and without known CSNB1) have identified variants in NYX." (PMID 41153400, 2025). "This suggests the possibility that some mutations in NYX could cause isolated myopia without night blindness, making it a reasonable candidate gene for isolated X-linked myopia." (PMID 17392683, 2007). "This study was designed to test the possibility that mutations in the NYX gene might cause high myopia without congenital stationary night blindness (CSNB)." (PMID 17392683, 2007). "Genes involved in the depolarization of ON bipolar cells include TRPM1, NYX, GPR179—detected in our described patient—and LRIT3, which, when damaged, similarly cause a negative ERG and are associated with high myopia." (PMID 40004769, 2025). "In addition, even without night blindness, some patients with NYX mutations may have myopia." (PMID 38448886, 2024). "Myopia is not always associated with CSNB, except in cases resulting from mutations in NYX and GRM6, suggesting a gene-specific phenotype rather than association with night blindness." (PMID 19862333, 2009).
myopia (continued). "The genomic sequence of NYX in 52 male probands with high myopia but without CSNB was analyzed through direct DNA sequencing." (PMID 17392683, 2007).
congenital stationary night blindness (7 papers, 2007 to 2023). "Up to date, more than 50 mutations in NYX have been reported to be associated with congenital stationary night blindness." (PMID 26234941, 2015). "Mutations in the nyctalopin gene (NYX) located at Xp11.4 are responsible for a complete form of congenital stationary night blindness (CSNB1)." (PMID 17392683, 2007). "Mutations in NYX have been reported to cause congenital stationary night blindness (CSNB1)." (PMID 17392683, 2007). "These infants also had congenital stationary night blindness (CSNB), reduced visual acuity, and mutations in either nyctalopin (NYX) or the L-type voltage-gated Ca-channel subunit 1F (CACNA1F) genes." (PMID 31513577, 2019). "These systemic syndromes can be caused by a series of genes, including NYX, CACNA1F, GRM6, and LRIT3, responsible for congenital stationary night blindness (CSNB); COL2A1, COL11A1, COL9A1, and COL9A2, responsible for Stickler syndrome; and FBN1, responsible for Marfan syndrome." (PMID 36980859, 2023).
Nystagmus (3 papers, 2015 to 2024). Rhythmic, involuntary oscillations of one or both eyes related to abnormality in fixation, conjugate gaze, or vestibular mechanisms. "The Riggs and complete types of TPRM1 gene mutations presented good visual acuity, whereas the incomplete and complete types of NYX gene mutations were frequently associated with poor visual acuity and nystagmus." (PMID 34064005, 2021).
Leber congenital amaurosis (2 papers, 2023 to 2025). Leber congenital amaurosis (LCA) is a retinal dystrophy defined by blindness and responses to electrophysiological stimulation (Ganzfeld electroretinogram (ERG)) below threshold, associated with severe visual impairment within the first year of life. "Examples include X-linked CSNB and Leber congenital amaurosis (LCA), caused by mutations in NYX and GUCY2D (respectively), where patients suffer a decreased ability to see in dimly lit environments that is usually present at birth or develops during adolescence." (PMID 37910517, 2023).
retinal disease (2 papers, 2011 to 2024). "Hendriks et al48 found that NYX and TRPM1 patients were in the top 3 myopic groups in a cross-sectional study in 302 patients with inherited retinal diseases." (PMID 38522615, 2024).
Blindness (1 paper, 2024). Blindness is the condition of lacking visual perception defined as a profound reduction in visual perception. "The risk of blindness tends to be higher in men due to a mutation in the nyctalopia gene (NYX) on Xp11.4 and X chromosome-related deficiencies in men." (PMID 38737755, 2024).
Hypercholesterolemia (1 paper, 2022). An increased concentration of cholesterol in the blood. "NYX-PCSK9i is a potential new therapy for hypercholesterolemia with the capacity to further enhance the lipid-lowering activities of statins." (PMID 36209894, 2022).
X-linked congenital stationary night blindness (1 paper, 2015). X-linked congenital stationary night blindness (XLCSNB) is a disorder of the retina. "NYX and CACNA1F genes are two disease-causing genes for X-linked congenital stationary night blindness." (PMID 26234941, 2015). "Mutations in NYX and CACNA1F gene are responsible for the X-linked congenital stationary night blindness (CSNB)." (PMID 26234941, 2015).
tumor (4 papers, 2012 to 2023). "Neither NYX nor PODNL1 mRNA was detected in either tissue type, while around 50% of healthy tissue samples showed variable levels of CHAD transcription, though it was totally absent in tumor tissue." (PMID 34440771, 2021).
NYX also shares sentences with these, for which no sentence is quoted: night blindness (3 papers); infection (2); X-linked retinoschisis (2); bacterial infection (1); behavior (1); choroideremia (1); Chudley-McCullough syndrome (1); cone-rod dystrophy (1); erosive vitreoretinopathy (1); fungal infections (1); leukaemia (1); liver cancer (1); lobular carcinomas (1); malaria (1); Marfan syndrome (1); Norrie disease (1); osteoarthritis (1); pituitary hormone deficiency (1); pneumonia (1); retinal disorder (1); retinal dystrophies (1); Stickler syndrome (1); Strabismus (1); X-linked familial exudative vitreoretinopathy (1).